LRG1 (leucine rich alpha-2-glycoprotein 1)
Diseases named in the same sentence as LRG1 in open-access papers (continued):
Sharing a sentence is not in itself a finding about the gene and the disease.
osteoporosis (3 papers, 2020 to 2025). A condition of reduced bone mass, with decreased cortical thickness and a decrease in the number and size of the trabeculae of cancellous bone (but normal chemical composition), resulting in increased fracture incidence. "Treatment with sEVs carrying high levels of LRG1 inhibits osteoclast differentiation in human BMDMs and in mice with osteoporosis, resulting in attenuated bone loss in mice." (PMID 37188819, 2023). "For example, increased hepatic SIRT2 expression promotes osteoporosis in aged mice and humans, while SIRT2 deficiency reduces bone resorption by upregulating LRG1 in sEVs, with LRG1 levels positively correlated with bone density." (PMID 40678144, 2025). "Here, we also identified LRG1-rich sEVs as an effective therapy for treatment of osteoporosis in mice." (PMID 37188819, 2023). "In osteoporosis rats, up‐regulation of miR‐497 or down‐regulation of LRG1 lowered LRG1 expression, which further suggested the participation of miR‐497 in osteoporosis by down‐regulating LRG1." (PMID 32975015, 2020). "Thereafter, the study is set out to delve into miR‐497/LRG1/TGF‐β1/Smads signalling pathway axis in osteoporosis." (PMID 32975015, 2020). "Rat osteoblasts were extracted from osteoporosis rats and transfected with restored miR‐497 or depleted LRG1 for further verification." (PMID 32975015, 2020). "One of the most significant findings demonstrated that miR‐497 expression reduced and LRG1 increased in osteoporosis." (PMID 32975015, 2020). "MiR‐497 and LRG1 expression in femoral head tissues and osteoblasts of osteoporosis rats were detected." (PMID 32975015, 2020). "In conclusion, our study reveals that miR‐497 is down‐regulated and LRG1 is upregulated in osteoporosis, and the increased miR‐497 or decreased LRG1 acts to alleviate the progression of osteoporosis via activating TGF‐β1/Smads pathway." (PMID 32975015, 2020). "Further investigations of the mechanism of miR‐497 and LRG1 should be explored in detail and performed with a larger cohort, so as to support a promising clinical application for patients with osteoporosis." (PMID 32975015, 2020). "Model rats were injected with restored miR‐497 or depleted LRG1 to explore their roles in osteoporosis." (PMID 32975015, 2020). "Moreover, our study has revealed that miR‐497/LRG1 axis mediated TGF‐β1/Smads pathway to affect osteoporosis." (PMID 32975015, 2020). "Besides that, this study has also concluded that miR‐497 restoration or LRG1 knockdown impaired oxidative stress, enhanced cell viability and inhibited apoptosis of osteoblasts in osteoporosis." (PMID 32975015, 2020). "Notably, treatment with AGK2 or LRG1-sEVs conferred a therapeutic benefit in osteoporosis, including in animal models and human primary cell cultures, corroborating targeting hepatocyte SIRT2 or sEV-LRG1 as a promising therapeutic modality in primary osteoporosis." (PMID 37188819, 2023). "We continued to verify the connection between LRG1 in sEVs (sEV-LRG1) and the protective role of SIRT2-KOhep in osteoporosis." (PMID 37188819, 2023). "MiR‐497 restoration or LRG1 knockdown activated TGF‐β1/Smads signalling pathway, promoted viability and suppressed apoptosis of osteoblasts in osteoporosis." (PMID 32975015, 2020). "MiR‐497 was poorly expressed while LRG1 was highly expressed and TGF‐β1/Smads signalling pathway activation was inhibited in osteoporosis." (PMID 32975015, 2020). "Here we mainly focused on primary osteoporosis without liver diseases and the correlation between hepatic LRG1 expression and primary osteoporosis still needs more clinical samples and further study." (PMID 37188819, 2023). "MiR‐497 up‐regulation or LRG1 down‐regulation activated TGF‐β1/Smads signalling pathway, promoted collagen type 1 synthesis and suppressed oxidative stress in femoral head tissues in osteoporosis." (PMID 32975015, 2020).
osteoporosis (continued). "In addition, our study also suggested that up‐regulation of miR‐497 or down‐regulation of LRG1 lowered OC, BALP, PINP and PICP contents, and promoted Col‐1 synthesis in osteoporosis." (PMID 32975015, 2020). "A negative relation was observed between miR‐497 and LRG1 (r = −0.6493, P = 0.0019) in femoral head tissues of osteoporosis patients by Pearson's correlation analysis." (PMID 32975015, 2020). "However, few researches have been conducted to expose the integrated role of miR‐497, leucine‐rich alpha‐2‐glycoprotein‐1 (LRG1) and transforming growth factor beta 1 (TGF‐β1)/Smads signalling pathway in osteoporosis." (PMID 32975015, 2020). "Riveting on our findings, up‐regulation of miR‐497 or down‐regulation of LRG1 could activate TGF‐β signalling pathway as accompanied by increased TGF‐β1, Smad3, Smad4 and p‐Smad2/3 protein expression and reduced Smad7 protein expression in osteoporosis." (PMID 32975015, 2020). "Our study suggests that miR‐497 up‐regulation or LRG1 down‐regulation promotes osteoblast viability and collagen synthesis via activating TGF‐β1/Smads signalling pathway, which may provide a novel reference for osteoporosis treatment." (PMID 32975015, 2020).
peripheral arterial disease (3 papers, 2017 to 2022). A disorder of the arteries supplying the upper and lower extremity and the visceral organs. "Increased LRG1 levels have been found in the plasma of T2DM patients and described as statistically significant predictors of peripheral arterial disease." (PMID 35062948, 2022). "Studies have also found LRG1 to be higher in patients with T2DM and peripheral arterial disease." (PMID 34441954, 2021).
peripheral arterial occlusive disease (3 papers, 2020 to 2024). "In the univariate analysis, a higher level of LRG1 was associated with the presence of cardiovascular disease (CVD) and peripheral arterial occlusive disease (PAOD)." (PMID 32249825, 2020). "Of note, LRG1 levels correlated positively with IL-6, a known activator of LRG1 gene expression, as well as with a more advanced state of T cell differentiation and the presence of cardiovascular disease and peripheral arterial occlusive disease demonstrating its potential systemic involvement." (PMID 38745756, 2024).
type 1 diabetes (3 papers, 2020 to 2024). "Similarly, in children with type 1 diabetes a clear relationship between plasma LRG1 and estimated glomerular filtration rate (eGFR) decline suggests that LRG1 may be an early marker of DKD progression." (PMID 38745756, 2024).
acute myeloid leukemia (2 papers, 2019 to 2022). Acute myeloid leukemia (AML) is a group of neoplasms arising from precursor cells committed to the myeloid cell-line differentiation. "LRG1 regulates tumor proliferation and apoptosis in acute myeloid leukemia (AML) cell lines, LRG1 expression increased in AML cells lines and LRG1 gene silencing could reduce cell viability and promote apoptosis." (PMID 36180909, 2022).
adult-onset Still disease (2 papers, 2020 to 2021). A rare inflammatory multisystem disorder characterized clinically by fever of unknown origin, arthralgia or arthritis, hyperleucocytosis, and typical skin rash. "We previously reported a study in adult-onset Still’s disease (AOSD) and found that urine α-1-acid glycoprotein 1 (LRG1), orosomucoid 1 (ORM1), and ORM2 might be new biomarkers of AOSD." (PMID 34489952, 2021).
Alzheimer disease (2 papers, 2022 to 2025). A progressive, neurodegenerative disease characterized by loss of function and death of nerve cells in several areas of the brain leading to loss of cognitive function such as memory and language. "Increased circulating LRG1 levels have been associated with neurodegenerative disorders such as dementia, Parkinson’s and Alzheimer disease and chronic social stress exposure in animals." (PMID 40473930, 2025). "Indeed, some authors showed that the CSF concentration of LRG1 is significantly higher in patients with Parkinson’s disease, dementia, progressive supranuclear palsy, idiopathic normal pressure hydrocephalus and Alzheimer’s disease compared to healthy elderly controls." (PMID 35062948, 2022).
cardiac hypertrophy (2 papers, 2015 to 2020). "Studies have shown that transient activation of Akt1 leads to reversible cardiac hypertrophy, which is associated with reduced expression of Lrg1 (GDS2304 / 1417290_at / Lrg1)." (PMID 28509980, 2015). "Together, the literature supports lower LRG1 expression being associated with cardiac hypertrophy." (PMID 28509980, 2015). "Analysis of cardiac phenotypes in Lrg1−/− with exercise or pressure overload-induced hypertrophy will provide valuable information regarding the role of LRG1 in physiological and pathological cardiac hypertrophy." (PMID 28509980, 2015). "The expression of LRG1 is significantly down-regulated in the left ventricle of hypertensive S.LWEx12x2x3x5 rat exhibiting concentric cardiac hypertrophy with augmented contractile function (GDS3873 _ 1374626_at _ Lrg1)." (PMID 28509980, 2015). "Further studies are required to elucidate the role of LRG1 in physiological cardiac hypertrophy." (PMID 28509980, 2015). "A reduced expression of LRG1 is observed in mouse models of pathological cardiac hypertrophy." (PMID 28509980, 2015). "LRG1 overexpression might be able to reverse cardiac hypertrophy induced by the activation of IGF1/PI3K/Akt1 pathway, exercise, pressure overload, and in α-TM E180G transgenic mice." (PMID 28509980, 2015). "Moreover, severe injury such as cardiac hypertrophy is displayed, which indicates the involvement of several DRGs of IL6, LUM, LRG1, PLG, with other molecules such as Alpha actinin, PDGF, Tgf beta, and TLR2 and TLR4." (PMID 32753925, 2020). "Understanding the role of LRG1 in TGFβ1 and IGF1 interactions may shed new light on the molecular mechanism of cardiac hypertrophy." (PMID 28509980, 2015).
Cirrhosis (2 papers, 2013 to 2023). A chronic disorder of the liver in which liver tissue becomes scarred and is partially replaced by regenerative nodules and fibrotic tissue resulting in loss of liver function. "There was the trend that patients with cirrhosis with decreased expression of hepatic LRG1 have lower bone mass, though the difference was not statistically significant." (PMID 37188819, 2023).
colorectal adenoma (2 papers, 2016 to 2024). An adenoma that arises from the colon or rectum. "A recent study found that serum biomarkers F5, ITIH4, LRG1, and VTN were elevated in colorectal adenoma patients as well as in a mouse model of colorectal adenomas." (PMID 38383428, 2024). "It was reported that plasma levels of LRG1 in patients with CRC were higher than those with adenomatous polyps, which might be a novel biomarker for the progression from colorectal adenoma to carcinoma." (PMID 26856989, 2016).
coronary artery disease (2 papers, 2023). "LRG1 has been shown to be elevated in animal models of retinopathy, in patients with coronary artery disease, in arterial stiffness, and, most recently, in animal models of cardiac fibrosis." (PMID 36979923, 2023).
dengue (2 papers, 2012 to 2020). "In the literature, LRG1 has never been associated to the dengue severity." (PMID 23101585, 2012).
depression (2 papers, 2020 to 2025). "The combination of increased LRG1 levels shows promise as a plasma-based diagnostic biomarker panel for detecting increased poststroke depression risk." (PMID 32317989, 2020). "Herein on the contrary, downregulation of both LRG1 and TREM1 was associated with depression only during pregnancy, in line with a possible pregnancy-only related signature." (PMID 40473930, 2025).
diabetic eye disease (2 papers, 2022 to 2025). A group of disorders affecting the eye in patients with diabetes mellitus. "This investigation establishes a mechanism of early initiating vascular dysfunction likely to be relevant to human diabetic eye disease, where LRG1 is found elevated in the plasma and vitreous." (PMID 41124286, 2025). "However, here, in the pre-neovascular stage of diabetic eye disease, LRG1 drives changes to the existing vasculature through paracrine signaling to pericytes." (PMID 41124286, 2025). "These correlative studies, plus the increasingly strong data around LRG1 involvement in AMD and diabetic eye disease, make a compelling case for assessment of therapeutic targeting of LRG1 in patients." (PMID 34987199, 2022).
hyperlipidemia (2 papers, 2023 to 2024). "For hyperlipidemia, only one previous study shows that LRG1 is a potential protein biomarker for coronary atherosclerosis in strain-treated patients with familial hypercholesterolemia, but its detailed level is not mentioned in the previous study." (PMID 38742172, 2024).
IgA nephropathy (2 papers, 2020 to 2022). "Besides DKD, other renal conditions have been associated with abnormal LRG1 secretion and include IgA nephropathy, where increased urinary LRG1 levels have been shown to correlate with disease severity, and paediatric idiopathic nephrotic syndrome." (PMID 35062948, 2022).
Kawasaki disease (2 papers, 2021 to 2024). A rare inflammatory disease characterized by an acute febrile, systemic, self-limiting, medium-vessel vasculitis primarily affecting children. "Nevertheless, LRG1 has been implicated in Kawasaki disease, an acute systemic vasculitis causing inflammation of small to medium sized blood vessels resulting in cardiovascular complications." (PMID 38745756, 2024). "Similarly, another study on Kawasaki disease in children identified LRG1 as a potential trigger of endothelial cell activation and cardiac remodeling that closely associated with IL-1β signaling." (PMID 38745756, 2024). "LRG1 specially expressed in the acute phase of kawasaki disease rather than in the convalescence of Kawasaki disease." (PMID 35095520, 2021).
kidney injuries (2 papers, 2020 to 2024). "First, we demonstrated that prenatal IA LPS induced CA-like responses in the fetal membranes, marked systemic immune responses at birth, and altered plasma levels of markers related to kidney injuries, including LRG1, ACE, and ICA." (PMID 33193334, 2020).
Lewis lung carcinoma (2 papers, 2015 to 2024). "Previous studies presented that overexpression of LRG1 promotes the apoptosis of cerebral ischemia/reperfusion injury, Lewis lung carcinoma cell lines, and cardiomyocytes in myocardial infarction model." (PMID 38707515, 2024).
ovarian tumor (2 papers, 2010). "Recently, elevated levels of LRG1 have been identified in chemoresistant ovarian tumor tissue, and in immunodepleted serum, using ICAT quantitative proteomics." (PMID 20831812, 2010). "Using RT-PCR, we also detected increased LRG1 mRNA expression in ovarian tumors compared to normal ovaries." (PMID 20831812, 2010). "Similarly, LRG1 expression levels were ~2 to 2.5-fold higher in ovarian tumor metastases than in normal ovaries." (PMID 20831812, 2010).
pancreatic ductal adenocarcinoma (2 papers, 2019 to 2021). An infiltrating adenocarcinoma that arises from the epithelial cells of the pancreas. "The abnormal expression of leucine-rich-alpha-2-glycoprotein 1 (LRG-1) is reported to be associated with multiple malignancies, but its role in the progression of pancreatic ductal adenocarcinoma (PDAC) remains to be determined." (PMID 30760292, 2019). "Molecular mechanistic research hinted that LRG1 strong enhance the cellular migration and invasion of pancreatic ductal adenocarcinoma cells in vitro through activation of the p38/MAPK signaling pathways (Xie ZB." (PMID 35095520, 2021). "A metabolite panel in combination with CA19-9, tissue inhibitor of metalloproteinase 1, and LRG1 exhibited substantially improved performance in the detection of early-stage pancreatic ductal adenocarcinoma." (PMID 35095520, 2021).
periodontitis (2 papers, 2024 to 2025). An acute or chronic inflammatory process that affects the tissues that surround and support the teeth. "LRG1 levels in serum and periodontal tissue are upregulated in periodontitis and are implicated in periodontal tissue destruction through interleukin‐6 production." (PMID 38656694, 2024). "They determined that LRG1 levels in serum and periodontal tissue are elevated in periodontitis and contribute toperiodontal tissue damage via interleukin-6 production." (PMID 40822769, 2025). "The correlation between the serum LRG1 levels and alveolar bone resorption in the mouse periodontitis model was also investigated." (PMID 38656694, 2024). "An area in the epithelial layer and connective tissue of the inflamed tissue obtained from patients with periodontitis stained strongly positive for LRG1 antibody." (PMID 38656694, 2024). "LRG1 levels in the periodontal tissue and serum in the periodontitis model were higher than those in control mice." (PMID 38656694, 2024). "The correlation between PISA, which quantifies the inflammatory area of periodontal pockets, and the LRG1 levels in the serum was evaluated to investigate the relationship between periodontitis and LRG1." (PMID 38656694, 2024). "Localization of LRG1 in human gingival tissues obtained from healthy volunteers and patients with periodontitis was determined." (PMID 38656694, 2024). "In vivo experiments were conducted to analyze LRG1 localization in periodontitis patients." (PMID 38656694, 2024). "Thus, it is necessary to investigate the major source of LRG1 that plays a dominant role in the progression of periodontitis." (PMID 38656694, 2024). "Similarly, P. gingivalis infection increased the amount of LRG1 in periodontal tissue and serum in the mouse periodontitis model." (PMID 38656694, 2024). "The findings of the present study demonstrated that serum LRG1 levels are correlated with PISA, the inflammatory surface area in patients with periodontitis." (PMID 38656694, 2024). "Previous studies have shown that basic periodontal treatment effectively reduces clinical symptoms and LRG1 levels in the serum and GCF of patients with grade III moderate periodontitis." (PMID 38656694, 2024). "This limitation underscores the need for future studies to investigate the amount of LRG1 in GCF as a biomarker in the pathology of periodontitis and for evaluating the treatment stage of periodontitis." (PMID 38656694, 2024). "Furthermore, LRG1 expression in the gingival crevicular fluid (GCF) and serum is increased in patients with severe periodontitis." (PMID 38656694, 2024).
pneumonia (2 papers, 2020 to 2023). An acute, acute and chronic, or chronic inflammation focally or diffusely affecting the lung parenchyma, caused by an infection in one or both of the lungs (by bacteria, viruses, fungi, or mycoplasma.). "The levels of LRG1 were increased in patients with lymphadenopathy, pneumonia, and pleuritis (p < 0.05); the levels of ORM1 were increased in patients with pericarditis and pneumonia (p < 0.05)." (PMID 33013889, 2020).
pulmonary TB (2 papers, 2020 to 2024). "A 6-protein diagnostic panel, comprising FETUB, FCGR3B, LRG1, SELL, CD14, and ADA2, differentiated patients with pulmonary TB from healthy controls and patients with other respiratory infections with high sensitivity and specificity in both cohorts." (PMID 38512356, 2024).
rectal cancer (2 papers, 2015 to 2021). A primary or metastatic malignant neoplasm that affects the rectum. "The biomarker signature was comprised of seven proteins (CADM1, LGALS3BP, HYOU1, FN1, VTN, LRG1, and MRC2) (Fig4A) that could predict the localization of rectal tumors especially well (86% of subjects with rectal cancer)." (PMID 26253080, 2015).
retinal disease (2 papers, 2020 to 2025). "In a study related to retinal disease mice model, LRG1 is found to interact with endoglin and promote pathogenic angiogenesis via promoting the TGF-β1/ALK1 signaling pathway." (PMID 32982792, 2020). "In the search for angiopathic factors that contribute to neovascular dysfunction, the secreted glycoprotein leucine-rich alpha-2-glycoprotein-1 (LRG1) has been identified as a possible candidate which contributes to the formation of dysfunctional neovessels in retinal disease." (PMID 40277918, 2025).